GPR146 (G protein-coupled receptor 146)
Description:
G protein-coupled receptor required for the regulation of plasma cholesterol levels. Receptor for CHLSN, a gut derived hormone which mediates an inhibitory effect of intestinal cholesterol absorption on hepatic cholesterol synthesis. Cholesin-binding exerts an antagonistic effect by inhibiting PKA signaling and suppressing SREBF2-controlled cholesterol in the liver.
Synonyms: PGR8
Tractability: Small molecule: it belongs to a druggable protein family. Antibody: UniProt places it where antibodies can reach, with high confidence; its Gene Ontology location is reachable by antibodies, with high confidence; UniProt predicts a signal peptide or a membrane-spanning region.
Target class: Family A G protein-coupled receptor; Membrane receptor
Gene: Protein-coding gene on chromosome 7 (1,044,537 to 1,059,269, forward strand). Ensembl gene ENSG00000164849.
Subcellular location: Cell membrane
Gene Ontology:
Molecular function: G protein-coupled receptor activity
Biological process: adenylate cyclase-inhibiting G protein-coupled receptor signaling pathway; regulation of cholesterol biosynthetic process; G protein-coupled receptor signaling pathway
Cellular component: plasma membrane; membrane
Homologues: Orthologues: chimpanzee GPR146 (99% identical), macaque GPR146 (96% identical), guinea pig GPR146 (78% identical), rat Gpr146 (74% identical), mouse Gpr146 (74% identical), dog GPR146 (73% identical). Paralogues in human: P2RY11 (15% identical), RXFP3 (14% identical), GPR151 (14% identical), GPR183 (14% identical), GPR174 (13% identical), GPR132 (10% identical), GPR141 (9% identical).
Diseases named in the same sentence as GPR146 in open-access papers:
GPR146 is named in the same sentence as 17 diseases in open-access papers, as found by Europe PMC text mining. Sharing a sentence is not in itself a finding about the gene and the disease. The quoted sentences say what the papers report.
atherosclerosis (6 papers, 2021 to 2025). A disease characterized by the build-up of fatty material and calcium deposition in the arterial wall resulting in partial or complete occlusion of the arterial lumen. "Studies in murine models have demonstrated that GPR146 deficiency confers significant protection against atherosclerosis, reducing lesion areas by up to 90% through an LDL receptor-independent mechanism." (PMID 38903815, 2024). "Although GPR146 has been extensively studied in the context of lipid-related disorders such as hypercholesterolemia and atherosclerosis, its role in other immune-inflammatory conditions is less understood." (PMID 38903815, 2024). "Depletion of GPR146 results in decreased levels of total cholesterol and triglycerides, emphasizing its potential role in atherosclerosis development." (PMID 38902687, 2024). "A non-coding variant rs1997243 regulates blood cholesterol levels through the upregulation of GPR146 expression and GPR146-/- mice are protected from hypercholesterolemia and atherosclerosis." (PMID 36766718, 2023). "Importantly, cholesin-GPR146 axis holds promise as a therapeutic target for hyperlipidemia and atherosclerosis, and the team already hinted at possible synergism with statin treatment." (PMID 38902687, 2024).
Hypercholesterolemia (4 papers, 2020 to 2024). An increased concentration of cholesterol in the blood. "Recent studies have found that the lack of GPR146 plays an important role in the prevention of hypercholesterolemia." (PMID 33180852, 2020).
Obesity (3 papers, 2021 to 2026). Accumulation of substantial excess body fat. "In mice, both constitutive and acute GPR146 depletion protect against diet-induced obesity and hepatic steatosis." (PMID 41775759, 2026). "A previous study showed that expression of GPR146 played an important role in insulin resistance, but these genes might be novel target for obesity." (PMID 34248836, 2021). "GPR146 mRNA was expressed in the livers of men, both with and without obesity, and in the adipose tissue of men with T1D, but not in the intestines." (PMID 40004948, 2025).
diabetes (2 papers, 2024). "We hypothesized that pathways downstream from GPR146 are active in cardiovascular-associated adipose tissues and may be affected by treatment of diabetes with SGLT2i." (PMID 38902687, 2024). "The integration of metabolic and immune pathways suggests potential therapeutic roles for C-peptide and G protein-coupled receptor 146 (GPR146) in diabetes and its sequelae." (PMID 38903815, 2024). "In this communication, we bring attention to the GPR146-related pathways in diabetes and their synergies with cardioprotective therapies such as SGLT2i." (PMID 38902687, 2024). "However, prior sources that investigated GPR146 before the identification of its ligand, demonstrated that its mRNA expression is also abundant across other tissues, including ones affected by diabetes complications." (PMID 38902687, 2024).
Hepatic steatosis (2 papers, 2024 to 2026). Steatosis is a term used to denote lipid accumulation within hepatocytes. "Here, we identify the orphan G protein-coupled receptor GPR146 as a regulator of hepatic steatosis through adipose-liver crosstalk." (PMID 41775759, 2026). "Intriguingly, the abrogation of GPR146 functionality is not correlated with elevations in hepatic enzymes, often employed as diagnostic indices for hepatic steatosis or non-alcoholic fatty liver disease." (PMID 38903815, 2024).
Insulin resistance (2 papers, 2021 to 2022). Increased resistance towards insulin, that is, diminished effectiveness of insulin in reducing blood glucose levels. "Recently, several GPCRs involved in the development of insulin resistance and pancreatic β-cell dysfunction, such as GPR119, GPR146, GPR40, GPR120, and TGR5, have received attention as targets for therapeutic interventions in diabetic patients." (PMID 35885041, 2022).
type 1 diabetes (2 papers, 2020 to 2025). "Although the robust expressions of c7orf50 and GPR146 in the adipose tissue of individuals with type 1 diabetes suggest a potential role of the cholesin system in adipose tissue, these findings must be interpreted with caution without data from an appropriate control group." (PMID 40004948, 2025).
breast carcinoma (1 paper, 2020). "If there is a significant association between GPR146 expression levels and breast cancer death or progression, it will strongly support the conclusion that C-peptide itself promote the cancer progression." (PMID 33180852, 2020). "Moreover, the cancer genome database showed that higher expression levels of GPR146 in patients with breast cancer." (PMID 33180852, 2020). "However, at present, there are no study about the causal link between the GPR146 and breast cancer death." (PMID 33180852, 2020).
gastric carcinoma (1 paper, 2020). A carcinoma that arises from epithelial cells of the stomach. "The knockdown of GPR146 inhibited C-peptide-induced c-Fos expression in the gastric carcinoma cell line KATO III." (PMID 33330513, 2020).
HCMV infection (1 paper, 2017). "In addition to these, HCMV infection of cord DCs resulted in a suppression of several other GPCRs [including GPR68, GPR183 (EBI2), and GPR146] that, together with C5AR1, CXCR4, and RGS18, have been shown to be highly enriched in unstimulated macrophages and dendritic cells." (PMID 28993767, 2017).
pulmonary hypertension (1 paper, 2024). Increased pressure within the pulmonary circulation due to lung or heart disorder. "Using a hypoxic pulmonary artery smooth muscle cell (PASMC) model and a hypoxic mouse model, researcher clarified the role of G protein-coupled receptor 146 (GPR146) in the regulation of lipid peroxidation in pulmonary hypertension." (PMID 39759448, 2024).
type 2 diabetes (1 paper, 2025). "In the present dataset, the mRNA expression levels of NPC1L1, c7orf50, and GPR146, respectively, were similar in the individuals with type 2 diabetes compared with the age-, sex-, and BMI-matched healthy individuals." (PMID 40004948, 2025).
cancer (3 papers, 2020 to 2023). A tumor composed of atypical neoplastic, often pleomorphic cells that invade other tissues. "Moreover, studies have shown that the copy number variations in the GPR146 gene are associated with many major diseases, including cancer." (PMID 33180852, 2020).
tumor (2 papers, 2022 to 2024). "These included genes consistent with pro-inflammatory immune responses (CD27, CD28, CD3e, CD8a, ICOS, ICOSLG, Pax5, TBX, GATA3, HLA-A, TNFSF14, GPR146), but also immune suppressive influences in the tumor immune microenvironment (CTLA-4, FoxP3, PD-1)." (PMID 36698398, 2022). "The tumor microenvironment’s immune composition was quantified using the CIBERSORT algorithm and the ESTIMATE method, which confirmed a positive correlation between GPR146 expression and immune cell infiltration." (PMID 38903815, 2024).
neurological disease (1 paper, 2016). "Analysis of the neurological disease network identified several key up-regulated targets such as HTR5A, KISS1R and GPR146." (PMID 27015368, 2016).
GPR146 also shares sentences with these, for which no sentence is quoted: juvenile idiopathic arthritis (1 paper); non-alcoholic fatty liver disease (1).